TNF (tumor necrosis factor)
Diseases named in the same sentence as TNF in open-access papers (continued):
Sharing a sentence is not in itself a finding about the gene and the disease.
Sepsis (continued). "Burn sepsis induced profoundly elevated levels of IL-1 β, IL-6, TNF-α, and MCP-1 in serum." (PMID 26550025, 2015). "Although the underlying pathophysiology of sepsis has not been completely elucidated, TNF-α and HMGB1 upregulation is known to play a crucial role in the systemic inflammatory response." (PMID 25930108, 2015). "Sepsis was the systemic inflammatory responses to infections, and the circulating macrophages played an important role during these responses through the release of inflammatory cytokines, such as IL-6 and TNF-α." (PMID 25625512, 2015). "The aim of this study was to investigate whether tumor necrosis factor-α (TNF-α), one of the major mediators of sepsis, inhibits glutamine-induced protein synthesis in the small intestine in a rat model of sepsis." (PMID 25574232, 2015). "High serum concentrations of TNF-α are correlated with sepsis-induced mortality." (PMID 25930108, 2015). "High serum levels of CXCL10, IL-6, IL-10, TNF and IL-8 were reported in a canine sepsis model." (PMID 26222498, 2015). "GTS-21, also known as DMBX-anabaseine, is a selective α7nAChR agonist that has been demonstrated to inhibit serum tumor necrosis factor (TNF) and high-mobility group box 1 in a dose-dependent manner in mice with lethal endotoxemia and sepsis and collagen-induced arthritis." (PMID 25009619, 2014). "TNF-α has been shown to be a major factor responsible for myocardial depression in sepsis." (PMID 25180066, 2014). "The local levels of IL-6 and TNF-α were also similar in WT, Nod1- and Nod2-deficient mice 24 h after severe sepsis induction (data not shown)." (PMID 25084278, 2014). "Finally, even if some cytokines, such as TNF and IL-10, are produced rapidly after the onset of sepsis, most of these proteic biomarkers need few hours to be generated, secreted and then, detected." (PMID 24658436, 2014). "In the context of sepsis, TNF-α, IL-1β, IL-6, and IL-8 are the most frequently altered cytokines." (PMID 24795771, 2014). "Synergically, TNF-α and IL-1 amplify the inflammatory signals by activating macrophages to produce proinflammatory cytokines such as IL-6 and IL-8, as well as lipid mediators and reactive oxygen species leading to sepsis-induced organ dysfunction." (PMID 25614712, 2014). "When sepsis occurs, multiple redundant inflammatory cytokines are released into the blood stream, including tumor necrosis factor-α (TNF-α), interleukin-6 (IL-6), leptin, C-reactive protein (CRP) and procalcitonin (PCT), which are important for mediating the inflammatory response." (PMID 24669245, 2014). "In conclusion Book and coworkers noted that up-regulation of HβD2 in sepsis occurred as a result of elevated pro-inflammatory cytokines (such as IL-1 and TNF) and was an indicator of higher activity of inflammation and the availability of sources other than peripheral blood cells for HβD2." (PMID 25027749, 2014). "Thus, exogenous H2S reduced kidney injury from urinary-derived sepsis by decreasing the levels of NF-κB and TNF-α, and increasing the level of IL-10." (PMID 25009602, 2014). "TNFα expression is also increased in the brains of both animals and humans during sepsis." (PMID 24886875, 2014). "GTS-21 has also been proven effective as an immunomodulatory drug that attenuates pro-inflammatory cytokine levels and improves survival in sepsis models, decreases severity in pancreatitis, and attenuates endotoxin-induced tumor necrosis factor (TNF) in lung tissue." (PMID 24719855, 2014). "Furthermore, the previous study showed that proinflammatory mediators, such as tumor necrosis factor-α (TNF-α) and interleukin-1β (IL-1β), played a critical part in myocardial dysfunction during sepsis." (PMID 24959004, 2014). "LPS-induced TNF-α may be a useful therapeutic candidate for the treatment of sepsis and other inflammatory diseases." (PMID 25253919, 2014). "The hypothesis for an effect on the LPS/TNFα interplay was based on previous findings of our group in models of sepsis." (PMID 24466134, 2014).
Sepsis (continued). "In addition, radix P. rubra significantly reduces plasma TNF-α levels and is effective in the treatment of sepsis." (PMID 24926378, 2014). "Therefore, TNF-α is a target molecule for the treatment of sepsis and ocular inflammatory disease processes." (PMID 25165412, 2014). "In part, this may reflect the timing of patient's enrollment, since in a previous work we found a dynamic modulation of ex-vivo induction of TNF-α and IL-6 in whole blood of septic patients related to the stages of sepsis." (PMID 24667684, 2014). "For example, TNF gene SNP rs1800629 is strongly associated with susceptibility to severe sepsis in the Chinese Han population, while genetic variants in TRAF6 are significantly associated with susceptibility to sepsis-induced acute lung injury." (PMID 24901344, 2014). "The acetylcholinesterase inhibitor neostigmine, which enhances cholinergic signaling by increasing acetylcholine levels, improved survival and reduced cytokine levels of TNF-α and IL-1β and attenuated neutrophil lung infiltration in a cecal ligation and puncture sepsis model." (PMID 25139304, 2014). "TNF, first described in 1975 for its in vivo capacity to kill tumor cells, was, six years later, shown to kill malaria parasites in vivo, and proposed, along with IL-1 (then known as LAF), to cause the disease complexities of malaria and sepsis." (PMID 24655719, 2014). "In the case of B. anthracis, TNF-α may also be involved in spore-induced sepsis in anthrax pathogenesis." (PMID 25472474, 2014). "High levels of TNF-α, IL-6, and IL-1β in the BALF have been noted in patients with ALI/ARDS, and the persistent elevation of proinflammatory cytokines in humans with ALI or sepsis has been associated with more severe outcomes." (PMID 25013450, 2014). "Additionally, d-galactosamine–sensitized mice, which are an in vivo model for sepsis, die because of macrophage-derived TNF-α, which is induced by 300 μg E. coli DNA or injection of 10 nmol ODN1668, a synthetic TLR9 ligand." (PMID 25472474, 2014). "In this report, we measured the levels of tumor necrosis factor (TNF)-α, interleukin (IL)-6 and IL-8 in severely burned patients with sepsis after the initiation of continuous vein-vein hemodiafiltration (CVVHDF) to evaluate the clinical usefulness of CVVHDF on the removal of key mediators." (PMID 27602373, 2014). "Although the debate regarding the use of animal models in the study of sepsis will continue, we believe the failure of anti-TNF-α treatments in clinical trials cannot continue to be used as an argument supporting the failure of animal studies to replicate human sepsis." (PMID 24265742, 2013). "AKI also leads to coagulation abnormalities and increased incidence of sepsis with multi-organ failure as well as to upregulation of cytokines (interleukin-1, interleukin-6, tumor necrosis factor-α) and/or immune-mediated major organ dysfunction (i.e. heart, lungs, and brain)." (PMID 23394360, 2013). "We suggest therefore that the direct effects of TNF-α on cell [Ca2+]i and contractility could contribute to whole-heart systolic dysfunction observed in sepsis." (PMID 24303157, 2013). "On the other hand, TNF also exerts host-damaging effects in sepsis and autoimmune disease." (PMID 24453410, 2013). "Treatment with XBJ led to a significant reduction in both cytokines releases, as compared with the sepsis-control group at the same time point, with the inhibition rate of IL-8 by 22.7%, 37.2%, and 38.5% and TNF-α by 45.4%, 32.1%, and 39.3%, at 6, 12, and 24 hrs after injection, respectively." (PMID 24369483, 2013). "We observed that PD decreased notably sepsis-induced serum TNF-α and IL-6 levels." (PMID 23431240, 2013). "To test this hypothesis, we attempted to suppress pro-inflammatory gene activity in RAG−/− mice by blocking TNF signaling with a neutralizing antibody, which has been shown to decrease IL-1β production in models of sepsis and arthritis." (PMID 24130499, 2013).
Sepsis (continued). "In other studies of experimental sepsis, TNF-α was either unchanged or increased." (PMID 24020447, 2013). "Consequently, mice fed diets supplemented with ω-3 PUFA suffered from increased infection-induced mortality associated with sepsis related serum LBP, IL-15 and TNF-α." (PMID 23405155, 2013). "Levels of TNF-α and IL-6 were increased already at 6 h after sepsis induction in both genotypes." (PMID 23397596, 2013). "In addition, the mean value of TNF-α at admission in sepsis group is statistically insignificant in comparison to SIRS group (P = 0.15)." (PMID 24175285, 2013). "TNF-α and IL-1 are the most important proinflammatory cytokines, they act synergistically in activating target cells and inducing the production of more inflammatory mediators and are largely responsible for the clinical manifestations of sepsis." (PMID 24363773, 2013). "TNFα is the main mediator and has an important role in acute kidney and lung injury in sepsis." (PMID 23837035, 2013). "ATF3 presents in the early stage (3 hrs) of endotoxemia to prevent macrophage activation and inhibit NO, IL-6, and TNF-α release that eventually will trigger an uncontrolled systemic inflammatory response that may lead to sepsis." (PMID 24062788, 2013). "Our results support a role for TNF bioactivity blockade in the treatment of sepsis, and suggest that different anti-TNF strategies may reach different survival rates through differentially attenuating inflammatory mechanisms." (PMID 23548047, 2013). "Also, TNF is a mediator in sepsis and we recently proved that the gut is an essential target in TNF's induction of systemic inflammatory response syndrome (SIRS), in a sepsis-like mouse model." (PMID 24339869, 2013). "IL1β, IL-6, and TNFα are believed to play a central role in sepsis-mediated myocardial depression." (PMID 23691359, 2013). "Furthermore, in a recent study by our group, gene transcripts of TREM-1 and of TNF were measured in circulating monocytes from 13 patients with severe sepsis and from seven patients with uncomplicated sepsis within the first 24 h diagnosis." (PMID 24350219, 2013). "In addition, levels of several inflammatory cytokines (TNF-α, IL-10, IL-1β), described as markers of sepsis, were reduced in galectin-3−/− mice." (PMID 23527230, 2013). "Lipopolysaccharide induces TNF-α release in cardiomyocytes which may be a major local source of TNF-α in the myocardium during sepsis." (PMID 23564188, 2013). "Also, there was a significant decrease in lung TNF-α concentration in propranolol treated rats at 24 hours when compared to six hours post sepsis onset (P <0.05, 95% CI -19.1 to -0.2)." (PMID 24020447, 2013). "Among the miRNAs which we found to be altered in TRAPS, MiR-150, miR-92 and miR-17 have been shown to be key regulators of specific lineage choices in the adaptive immune system and serum miR-150 levels have recently been negatively correlated with the plasma TNF-α levels in patients with sepsis." (PMID 24066048, 2013). "TNF-alpha induces monocytes to secrete other cytokines, such as IL-1, IL-6, and IL-8, which are essential for controlling infection and cleaning LPS from blood, and is also involved in sepsis and tissue lesions." (PMID 24130911, 2013). "The protective role of IL-10 in animal sepsis may be due to its antagonistic effect on the production and overall functioning of TNF." (PMID 23548047, 2013). "The plasma concentration of TNF-α reported in patients with sepsis is around 1 ng/mL." (PMID 24303157, 2013). "Furthermore, the IL-10/TNF-alpha ratio has been proposed as a prognosis indicator in sepsis during leptospirosis." (PMID 24130911, 2013). "Sepsis, a life-threatening disease with a high mortality rate, is accompanied by systemic inflammation with excessive production of pro-inflammatory cytokines including tumor necrosis factor-α (TNF-α) and interleukin-1β (IL-1β)." (PMID 24260470, 2013).
Sepsis (continued). "The suppression of the TNF-α release is another important factor, since it is considered a potent mediator in sepsis from various evidences, since it is first cytokine that appears in the circulation in human sepsis." (PMID 23737945, 2013). "In this way, the modulation of local myocardial TNF-α levels produced by cardiomyocytes may be of therapeutic significance in sepsis-induced myocardial dysfunction." (PMID 23564188, 2013). "Not only TNF-α but also HMGB1 plays a crucial role in lethality during sepsis." (PMID 24098466, 2013). "Sepsis enhances the transcription of several pro- and anti-inflammatory cytokines and chemokines in the brain, including tumor necrosis factor alpha (TNFα), interleukin-1 beta (IL1β), transforming growth factor beta (TGF β), and monocyte chemoattractant protein 1 (MCP1)." (PMID 23718252, 2013). "However, a disconnect exists between hyper-acute experimental animal models and human sepsis illustrated by the failure of several clinical trials of anti-TNF-α monoclonal antibodies." (PMID 23710641, 2013). "However, our experiments demonstrated that the levels of IL-6 and TNF-α in serum and peritoneum, and cytosolic IL-1β and IL-10 expression in macrophages were similar between WT and Nod2−/− mice during sepsis." (PMID 23675299, 2013). "Apoptosis in renal cells occurs through TNF-α and Fas ligand-mediated pathways during sepsis." (PMID 23476127, 2013). "Furthermore, in vivo studies in dogs have demonstrated that injection of TNF-α can replicate the profile of systolic and diastolic dysfunction observed in sepsis." (PMID 24303157, 2013). "Inhibition of JAK2 and STAT3 tyrosine phosphorylation may reduce TNF-α level in sepsis in vivo, indicating TNF-α is also involved in the JAK2/STAT3 pathway in anti-inflammation." (PMID 23840548, 2013). "Thus, TNF-α-mediated lung inflammation and kidney dysfunction are established early in the course of experimental sepsis." (PMID 24265742, 2013). "As TNF-α and IL-1β mediate most of the physiological disturbances which are characteristic for sepsis, it is possible that the down-regulation of PNoc and NOP in peripheral blood cells might restrict the production of pro-inflammatory cytokines." (PMID 24066107, 2013). "Furthermore, TNFα and IL-6 are considered biomarkers of sepsis, and in this study their levels were reduced locally by MAT.Ang-1 during endotoxemia." (PMID 23036162, 2012). "As TNF-α plays a pivotal role in the pathogenesis of severe sepsis in response to infection, it is reasonable to assume that patients with rs1800629A allele might produce a higher amount of TNF-α, and therefore become more susceptible to severe sepsis." (PMID 23029405, 2012). "The pathways of apoptosis in sepsis may involve activation of the extrinsic (TNF-α/TNFR and Fas/FasL) and/or intrinsic (mitochondrial) pathways, the final steps being activation of caspases that cause apoptosis of T and B cells." (PMID 23208733, 2012). "Moreover, positive relationships between Ang2 and inflammatory cytokines, such as tumor-necrosis factor (TNF)-alpha and interleukin (IL)-6 are observed in severe sepsis." (PMID 23021336, 2012). "Moreover, intravenous infusion of TNF can elicit many of the characteristic abnormalities of sepsis." (PMID 22664467, 2012). "IL-6 and TNF-α appeared to be good markers for predicting severity and prognosis of sepsis." (PMID 22731930, 2012). "The results obtained strongly suggest that high levels of circulating TPO in patients with sepsis may favor the occurrence of myocardial depression in cooperation with TNF-α and IL-1β." (PMID 22577249, 2012). "Furthermore, studies have shown that levels of TNF-α, IL-1β, and IL-6 are markedly increased in patients with established sepsis." (PMID 22655058, 2012). "Tumour necrosis factor-α (TNF-α) is one of the important mediators of inflammation in sepsis, and may alter mitochondrial function in human hepatocytes." (PMID 23028840, 2012).
Sepsis (continued). "The most important inflammatory mediators in myocardial depression in sepsis are TNF-α and IL-1." (PMID 22482045, 2012). "High circulating levels of TNF-α were correlated with poor outcomes in sepsis patients." (PMID 23029405, 2012). "According to our data and data from other investigators, in clinical/experimental sepsis the large amount of TNFα production and its detrimental effects for the host may be controlled by PCT release." (PMID 22568957, 2012). "Moreover, we found that TNF-α serum levels in severe sepsis patients with AA+AG genotypes for rs1800629 were significantly higher than those in the individuals with GG genotype." (PMID 23029405, 2012). "Inhibitory effect of compound 6e on IL-6 and TNF-α secretion in an animal model of sepsis." (PMID 22664467, 2012). "Blood levels of TNF and IL-6 are high in most patients with severe sepsis." (PMID 22664467, 2012). "At a very early stage of sepsis, although baicalin blocked initiation of inflammatory responses, neutrophil- or macrophage-derived cytokines, such as TNF-alpha, ROS, and NO, might trigger apoptosis." (PMID 22590504, 2012). "In short, although there was a trend of beneficial effect for anti-TNF to reduce sepsis-associated risk of death, none of these trials showed significance." (PMID 23049598, 2012). "Furthermore, we measured TNF-α serum concentrations in 120 severe sepsis patients, including 104 patients with rs1800629GG genotype, 14 patients with GA genotype and 2 patients with AA genotype." (PMID 23029405, 2012). "TNF-α is one of the important mediators of the inflammatory response seen in sepsis/septic shock and may also induce mitocondrial dysfunction in human hepatocytes." (PMID 23028840, 2012). "Moreover, in patients with severe sepsis, individuals with AA+AG genotypes had significantly higher TNF-α serum concentrations than those with GG genotype (Padj = 0.02)." (PMID 23029405, 2012). "Our findings suggested that the functional TNF gene SNP rs1800629 was strongly associated with susceptibility to severe sepsis, but not with lethality in Chinese Han population." (PMID 23029405, 2012). "The objective of this study was to investigate whether genetic variation in TNF, LTA, TNFRSF1A and TNFRSF1B was associated with susceptibility to or death from severe sepsis in Chinese Han population." (PMID 23029405, 2012). "TNFα is a key proinflammatory cytokine involved in mediating endotoxemia and sepsis." (PMID 22420504, 2012). "These fragments have been shown to neutralize TNF in the lung in severe sepsis patients." (PMID 22340283, 2012). "Inhibition of TNFα production therefore has a high therapeutic potential in managing sepsis." (PMID 22420504, 2012). "However, trials with a variety of intact antibodies, fragment antigen-binding (Fab) dimers and soluble receptors against TNF have so far shown only limited signals of efficacy in sepsis." (PMID 22340283, 2012). "Role of TNFα is well documented in sepsis and has also been shown in SIRS." (PMID 23110185, 2012). "In a sepsis simulation model, we tested whether the anesthetic ketamine inhibits the macrophage TNF response to antibiotic-exposed CA-MRSA bacteria via its antagonism of N-methyl-D-aspartate (NMDA) receptors." (PMID 21266054, 2011). "In addition, we also found that TNF-α, IL-6, and IL-10 levels were significantly lower in plg-/- mice than in WT mice during sepsis." (PMID 21931850, 2011). "To determine whether 5HD treatment affects the local inflammatory response in the septic rat heart, we determined the concentration of TNF-α in the supernatant of the harvested heart samples in the sham and sepsis groups." (PMID 21712982, 2011). "Inhibition of IL-1β in sepsis was more profound than tumour necrosis factor (TNF)." (PMID 21244670, 2011).